EGFR (epidermal growth factor receptor)
Diseases named in the same sentence as EGFR in open-access papers (continued):
Sharing a sentence is not in itself a finding about the gene and the disease.
cancer (continued). "Our results are in agreement with those of Farin and coll., that suggested the use of aptamer-targeting NCL on GB cell lines, as a new strategy to inhibit the activation of EGFR- and Ras-driven cancers." (PMID 26540346, 2015). "A recent study reported the anticancer effects of AECS against epidermal growth factor receptor (EGFR)-dependent cancers." (PMID 26593947, 2015). "After ignoring this cross-talk, the next best cross-talk in terms of gene count is between “signalling by NGF” with the same set of pathways as in CM i.e. “signalling by FGFR in disease”, “signalling by EGFR in cancer” and “signalling by PDGF”." (PMID 26558755, 2015). "It has been reported that the activation of EGFR stimulated cellular calcium signaling and promoted the growth of cancer cells." (PMID 26542098, 2015). "Some studies suggest that NT can stimulate many cancer proliferation in an EGFR-dependent mechanism, including foregut neuroendocrine tumor, prostate, colon and non-small cell lung cancers." (PMID 26215716, 2015). "Cancer cells that have acquired resistance to single-target EGFR inhibitors remain sensitive to CUDC-101." (PMID 25940539, 2015). "Since co-expression of HER2 and EGFR has been reported to be related with a poor prognosis in several types of cancer, a bispecific affibody directed against these receptors was generated." (PMID 26635612, 2015). "HuR is phosphorylated at tyrosine residues in tumor cells and has several consensuses for phosphorylation by Abl-1, SRC, Lyn, FAK, and EGFR tyrosine kinases, involved in aberrant regulation of centrosomes in cancer cells." (PMID 25803745, 2015). "In the present study, we further demonstrated that up-regulation of c-Cbl in vitro and in vivo mediated HDACi-induced EGFR degradation and anti-cancer effect on NSCLC." (PMID 25980579, 2015). "The first is that activation of the Mapk/ERK pathway via EGFR stimulation is vital for increased transcription of numerous cancer related genes." (PMID 25802834, 2015). "Another recent study demonstrated that ART activity in cancer cells is mediated by signaling pathways downstream of EGFR." (PMID 26426994, 2015). "The promoter role of EGF during tumorigenesis has been very well recognized and its receptor (EGFR) is presently a target for many cancer therapies." (PMID 26431493, 2015). "The dynamics of signaling activation downstream of EGFR, as a function of time, can also provide cancer cells with potential resistance mechanisms against EGFR-targeted inhibition." (PMID 25885672, 2015). "Inhibition of FASN or palmitoyl acyltransferases reduced the activity and down-regulated the levels of EGFR, and sensitized cancer cells to EGFR tyrosine kinase inhibitors." (PMID 26378037, 2015). "EGFR belongs to the HER/ErbB family of tyrosine kinase receptors and its activation in cancer cells has been linked with increased proliferation, angiogenesis, and metastasis." (PMID 25699271, 2015). "By querying K-Map with the essential kinases mediating resistance to EGFR-inhibitor gefitinib in an EGFR mutant non-small cell lung cancer (NSCLC) cell line, bosutinib was predicted to be a more effective drug for killing EGFR mutant cancer cells." (PMID 25741385, 2015). "Growing evidence reveals that epidermal growth factor receptor (EGFR) plays a pivotal role in tumorigenesis, drug resistance, relapse and the metastasis of various cancers." (PMID 25730907, 2015). "In cancer treatment with anti-EGFR antibodies and small molecule drugs that inhibit EGFR tyrosine kinase activity, autophagy is often induced." (PMID 25909451, 2015).
cancer (continued). "To expand these analyses, we examined the collection of 10 EGFR mutant cancer samples (from 9 patients) that underwent transformation to SCLC at the time of acquired resistance as well as the 11 resistant controls that had maintained NSCLC histology." (PMID 25758528, 2015). "Epidermal growth factor receptor (EGFR) and receptor tyrosine-protein kinase 3 (ErbB3) are two well-established targets in cancer therapy." (PMID 25997020, 2015). "Taking into account that EGFR is required for IL-10- and LPS-stimulated macrophage-mediated invasion, we evaluated if both macrophage populations differently affected cancer cell EGFR signalling." (PMID 26043921, 2015). "When fixed concentrations of JAKi were incubated with increasing concentrations of the EGFR inhibitor gefitinib, highest anti-cancer activity was seen in the highest combined doses." (PMID 25928246, 2015). "EGFR is a receptor tyrosine kinase that is overexpressed in a variety of human epithelial malignancies, such as carcinomas of the lung, colon, ovary, bladder and head and neck." (PMID 25652422, 2015). "As shown in this figure, EGFR and ErbB-3 are primarily expressed in human carcinomas (50% ∼ 70%); ErbB-2 is expressed in 20% ∼ 30% of these carcinomas; and the expression of ErbB-4 occurs only in breast and colon carcinomas." (PMID 25993617, 2015). "Deregulation of epidermal growth factor receptor (EGFR) signaling has been correlated with the development of a variety of human carcinomas." (PMID 25762314, 2015). "For example, streptadivin-coated fluorescent polystyrene nanospheres offer greater sensitivity in the detection of epidermal growth factor receptor (EGFR) in human carcinoma cells, thus providing a more sensitive tool for biomarker discovery." (PMID 28347058, 2015). "By immunohistochemistry, EGFR overexpression was identified in 52 of the 90 (57.8%) cases, and in 46 of the 64 triple-negative (71.9%) carcinomas." (PMID 26115045, 2015). "As the EGFR signaling pathway is well-acknowledged as a leading pathway during the development of many carcinoma types, EGFR has become a rational and important therapeutic target." (PMID 25993617, 2015). "Evidence suggests that EGF and its receptor EGFR are involved in the pathogenesis and progression of different carcinoma types." (PMID 26648665, 2015). "EGFR plays a crucial role in cancer because it is a receptor for a wide variety of ligands including amphiregulin, betacellulin, EGF, epigen, epiregulin, heparin binding EGF-like growth factor (HB-EGF), and type α transforming growth factor (TGF-α)." (PMID 25401099, 2014). "It is known that EGFR signaling plays an important role in cell migration and invasion in multiple types of cancer." (PMID 25395181, 2014). "Research into the role of the Notch–EGFR crosstalk has since been observed in lung, skin, and brain cancers." (PMID 25566499, 2014). "An epidermal growth factor receptor (EGFR) has been validated as a promising therapeutic target for cancer." (PMID 24422746, 2014). "The expression level of E-cadherin and ZEB1 is a useful indicator of cancer cell sensitive to target therapy including epidermal growth factor receptor (EGFR) tyrosine kinase inhibitors, gefitinib, and erlotinib." (PMID 25197668, 2014). "EGFR, which shares close structural homology with ErbB2, has been shown to be a client of Hsp90 and has maintained stability in many cancer cells." (PMID 24722501, 2014). "It has also been well documented that overexpression of Survivin and EGFR contributes to tumorigenesis in many different types of cancer." (PMID 24728382, 2014). "Although the role of EGFR overexpression in cancer progression is well established, the role of p27Kip1 is much less clear." (PMID 25121353, 2014). "Research on erbB receptors has long been focused on dysregulation of tyrosine kinase activity of EGFR and erbB2 in human cancers." (PMID 24886126, 2014).
cancer (continued). "EGFR-mediated signaling pathways are known to be a driving force in lung tumorigenesis and have been extensively investigated as targets for cancer therapy." (PMID 24662938, 2014). "Mainly, the transactivation of epidermal growth factor receptor (EGFR) family members mediates the mitogenic activity of different CKs in human cancer." (PMID 25484899, 2014). "The Akt phosphorylation that is induced by EGFR signaling is attenuated in the absence of CNOT9, which suggests that CNOT9 enhances EGFR signaling and contributes to carcinogenesis and progression of cancer, particularly in mammary glands." (PMID 25191340, 2014). "Cancer progression has been correlated with the increase in the number of EGFR molecules on the cell surface." (PMID 25386651, 2014). "Further, to appreciate the insights of differential cancer networks and their applications, a detailed work out of SpliceNet on Bcl-x and EGFR centered network is illustrated." (PMID 25034693, 2014). "Among the 73 cancer amplified genes were a number of established drug targets, such as EGFR, ERBB2 and KIT." (PMID 24874471, 2014). "High levels of expression and activation of EGFR are common in human cancer cells and it is well documented that a large number of NSCLCs overexpress EGFR." (PMID 24456610, 2014). "In cancer, majority of growth factor receptor protein tyrosine kinases such as EGFR, HER2/3, FGFR, PDGFR, IGFR were found to be hyper activated." (PMID 25466244, 2014). "The major function of Hsp90 is to maintain the stability and activity of multiple kinases, transcription factors and steroid receptors, many of which are dysregulated in human cancer, such as Raf-1, EGFR and AKT." (PMID 24662070, 2014). "Secondly, an inverse correlation of p27 and EGFR expression was observed in clinical human cancer tissues." (PMID 25121353, 2014). "In contrast, an inverse correlation was found between hamartin and p-EGFR Tyr-992 in SCC specimens indicating different molecular fingerprints in different cancer subtypes." (PMID 24593867, 2014). "The present data also supports our previously publish results showing that low dose UVB illumination of cancer cells overexpressing EGFR (A431 and Cal39) led to the arrest of the EGFR signaling pathway." (PMID 25386651, 2014). "Targeted therapies are used depending on the cancer genotype or stage of disease and includes erlotinib, a small molecule inhibitor directed against epidermal growth factor receptor (EGFR)." (PMID 24551227, 2014). "Abnormal phosphorylation of Akt and Erk1/2 was considered as an important factor in the prognosis of cancer and constitutive activation of EGFR–Akt–mTOR was found in about 18% of NSCLCs." (PMID 24629040, 2014). "Immunohistochemistry of patients' cancer tissues revealed that ARNO over expression was correlated with enhanced EGFR and IGF-IR." (PMID 24618737, 2014). "We have previously shown that low dose UVB illumination of cancer cells overexpressing EGFR prior to adding EGF halted the EGFR signaling pathway." (PMID 25386651, 2014). "Another difference in the time course data between the three cancer cell lines is shown by the expression level of EGFR." (PMID 24820097, 2014). "Several recent studies have indicated that VeriStrat classification has significant power to predict response to EGFR inhibitors for several cancer types." (PMID 24722523, 2014). "Here, we will discuss two examples of membrane proteins important for cancer research and immunotherapy: the epidermal growth factor receptor (EGFR) and the vascular endothelial growth factor receptor (VEGFR)." (PMID 25101077, 2014). "EGFR has been found to contribute the lung development and multiplicity of cancer-related signal transduction pathways like cellular proliferation, adhesion, migration, neoangiogenesis, and apoptosis inhibition." (PMID 24629040, 2014).
cancer (continued). "Our findings implicate the NTS/NTSR1 complex as a contributor to cancer aggressiveness by enhancing concomitantly the expression and activation of three receptors EGFR, HER2, HER3." (PMID 25249545, 2014). "Out of the four isoforms of EGFR, NM_201283 and NM_201284 have edges only in cancer samples suggesting their importance in tumorigenesis when compared to other two isoforms." (PMID 25034693, 2014). "This is important because EGF/EGFR axis is known to regulate cancer cells to proliferate and migrate to distant sites." (PMID 24811863, 2014). "For instance, biocompatible block co-polymer micelles containing Pc4 PS were surface-modified with epidermal growth factor receptor (EGFR)-targeting GE11 peptides for active targeting of EGFR-overexpressing cancer cells." (PMID 25317253, 2014). "We first investigated the contribution of miR-146a to cell growth and apoptosis in HCC cells and also compared the effect of miR-146a mimic to the siRNA specially targeting EGFR mRNA, since EGFR was documented as a target of miR-146a in various cancers." (PMID 24895573, 2014). "The human epidermal growth factor receptor (HER) family plays a major role in cancer cell proliferation." (PMID 25594012, 2014). "DAVID ontology analysis revealed enrichment of cancer-associated pathways, including the well-characterized cancer genes MTOR, EGFR, AKT1, and CASP8 in the region of overlap." (PMID 25294808, 2014). "In our dataset, due to scarcity of data on cancer treatment, we were unable to examine the important question of the predictive value of KRAS mutations in relation to anti-EGFR therapy." (PMID 24885062, 2014). "Third, this RTKs-targeting degradation strategy can be combined with antibodies or small molecule inhibitors against RTKs, especially when kinase-independent biologic functions of RTKs, such as IGF-1R and EGFR, also contribute to cancer malignancy." (PMID 24970814, 2014). "Not surprisingly, the overexpression of ERBB3 has been frequently detected in many types of human cancers, and accumulating evidence strongly suggests that ERBB3 plays a crucial role in cancers driven by EGFR and ERBB2." (PMID 24970817, 2014). "It has been proposed that the epidermal growth factor receptor (EGFR) pathway is important for cancer pathophysiology." (PMID 24457059, 2014). "The IR is not the only RTK associated with the IGF-1R; for example, a direct interaction between the IGF-1R and EGFR was identified in cancer cells, with EGFR depletion affecting IGF-1R ubiquitination, degradation, and signaling." (PMID 24276851, 2014). "Since the activating mutation of EGFR plays a central role in the dysregulation of gefitinib-resistant H1650 NSCLC cells, the degradation of EGFR will contribute remarkably to inhibit the proliferation of these EGFR survival dependent cancer cells." (PMID 24662070, 2014). "Understanding the detailed mechanism of EGFR internalization is crucial regarding the connection of EGFR and cancer." (PMID 25520666, 2014). "Our results demonstrate that p27Kip1 down-regulation plays a key role in up-regulating the JNK/c-Jun pathway, leading to increased EGFR expression and anchorage-independent growth and endowing these cancer cells with a new metastatic potential." (PMID 25121353, 2014). "EGFR and Notch are part of the signaling pathways involved in cancer and these pathways are frequently altered in brain carcinogenesis." (PMID 23771628, 2014). "EGFR is overexpressed in many human cancers and its activation leads to increased cell growth and proliferation through numerous signaling pathways." (PMID 26056585, 2014). "Previous studies have indicated that crosstalk between IGF1R and other tyrosine kinases such as HER2 and EGFR can drive cancer progression and drug resistance." (PMID 24655723, 2014). "This is consistent with the presence of a NTS autocrine loop, leading to the sustained activation of EGFR and responsible for cancer aggressiveness." (PMID 25249545, 2014).
cancer (continued). "The EGFR signaling is complex and known to be involved in multiple diseases especially certain types of cancer." (PMID 25036103, 2014). "Correlated with the density of EGFR expression level on these cancer cells, EGFR-mediated uptake of the micelle (EGF+) was increased." (PMID 25379530, 2014). "Emerging data from in vitro studies with gastric and colorectal cancer cell lines demonstrated a synergistic effect of EGFR-inhibitors and irinotecan." (PMID 25272957, 2014). "We were particularly interested in EGFR because of its positive roles in cancer cell migration and invasion and its overexpression in EOC." (PMID 24816687, 2014). "We report, for the first time, that the EGFR mutations T725M and L861R, which are infrequently observed in cancers, constitutively activate EGFR in a manner analogous to the frequently observed driver mutations." (PMID 24743239, 2014). "Accumulating evidence suggests that EGFR translocates to the nucleus both in normal and cancer cells alike." (PMID 25416285, 2014). "Respiratory problems are also associated with use of gefitinib, an anti-cancer epidermal growth factor receptor (EGFR) inhibitor that also inhibits GAK." (PMID 25009465, 2014). "Blocking the binding of EGF to EGFR can abolish cancer proliferation, invasion, metastasis, angiogenesis and inhibition of apoptosis." (PMID 25386651, 2014). "The findings in the report for EGF receptors also propose an alternate therapeutic approach using OP as an anti-cancer agent targeting Neu1 sialidase as the key central enzyme within this novel EGFR signaling platform." (PMID 26932374, 2014). "Genistein derivatives inhibited clonogenic growth of HCT 116 cancer cells additively or synergistically when used in combination with ionizing radiation, and decreased EGFR activation." (PMID 25401399, 2014). "Nonreceptor tyrosine kinase Src is often activated in various types of cancer via mutations or growth factor signaling pathways including insulin-like growth factor-1 receptor (IGFR-1), EGFR, and platelet-derived growth factor receptor (PDGFR)." (PMID 25302298, 2014). "EGFR, JAK tyrosine kinase, Src tyrosine kinase and Erk1/2 play a dominant role in STAT3 phosphorylation and are linked with cancer cell proliferation, metabolic regulation and metastasis." (PMID 24799285, 2014). "The EGFR pathway is crucial in normal growth of human organs but under certain conditions, EGFR serves as a stimulus for cancer growth." (PMID 25486251, 2014). "BIM expression in treatment naïve cancers predicts responsiveness to EGFR TKIs, but almost 2/3 of patients have low BIM mRNA levels at baseline." (PMID 25364578, 2014). "Associations of KRAS mutational status with progression, treatment outcome, and response to EGFR-based treatment have been reported in both of these cancers." (PMID 25158139, 2014). "The chemokine network and CXCL12/CXCR4 signaling in particular, as well as EGFR signaling are involved in many aspects of cancer biology, including growth and metastasis." (PMID 24906407, 2014). "We previously reported that HDAC inhibitors potentiate radiation-induced cell killing in a panel of human cancer cells with activated EGFR signaling through diverse mechanisms." (PMID 24418474, 2014). "As typified by EGFR-targeted therapies for metastatic CRC (e.g.: panitumumab and cetuximab), this modest response is attributed to the innate and acquired proficiency of cancer cells to escape EGFR inhibition by engaging alternative oncogenic signals." (PMID 24708867, 2014). "The epidermal growth factor receptor (EGFR) is frequently overexpressed in malignant tumors, and its level is correlated with increased cellular radioresistance." (PMID 25302298, 2014). "We have identified previously another signaling pathway under EGFR, which mediates invasive and motile phenotypes of cancer cells." (PMID 24621372, 2014).